ADAM9 (ADAM metallopeptidase domain 9)
Diseases named in the same sentence as ADAM9 in open-access papers (continued):
Sharing a sentence is not in itself a finding about the gene and the disease.
tumor (continued). "Interfering with ADAM9 expression in primary PCa interrupts the formation of the vicious cycle between primary PCa cells and OBs, impairing PCa-OB formation, tumor growth and metastatic spread." (PMID 36778124, 2023). "ADAM9 levels were overexpressed in tumor tissue from PCa patients; ADAM9 blockade interrupted OB-induced release of WISP-1 and also suppressed primary tumor growth and distal metastasis in orthotopic PCa mouse models." (PMID 36778124, 2023). "The results of this study suggest that ADAM9 is one of the targets regulated by miR-126 in GC cells and in this process, miR-126 performs its potential tumor suppressive function in GC." (PMID 37185715, 2023). "The interplay between platelet α6β1 and tumor ADAM9 facilitates tumor cell intravasation and extravasation, as evaluated by the trans-endothelial migration in vitro and in vivo." (PMID 36937386, 2023). "In vivo, circ-ADAM9 silencing or miR-217 overexpression delays the growth of the tumor, and their combination shows an obvious inhibitory effect on tumourigenicity." (PMID 37170188, 2023). "In androgen-independent PCa, ADAM9 can form a complex with N-α-acetyltransferase 10 protein to maintain ADAM9 protein stability and thus promote tumor cell invasiveness and in vivo tumor progression." (PMID 36778124, 2023). "Silencing of ADAM9 expression encourages apoptosis in various tumor cells, such as ovarian and prostate cancer." (PMID 36717861, 2023). "shRNA-mediated depletion of ADAM9 in primary PCa cells suppressed the formation of PCa-OBs in bone, as well as PCa tumor growth and distal metastasis in an orthotopic PCa mouse model." (PMID 36778124, 2023). "Research conducted by The Affiliated Tumor Hospital of Zhengzhou University showed a correlation between the expression of miR-126 and the regulation of critical metastatic molecule ADAM9 (ADAM metallopeptidase domain 9, a component of cell–cell junctions)." (PMID 38132441, 2023). "Although most studies related to ADAM9 focused more on its effect on tumour proliferation, migration, and invasion, various studies have pointed out the value of ADAM9 for tumour drug therapy." (PMID 37082201, 2023). "The study also identified ADAM9, which is expressed on tumor cells, as the counter receptor of α6β1." (PMID 36937386, 2023). "ADAM9, which is connected to tumor cell proliferation, invasion and inhibition of apoptosis, is also upregulated in HCC cells." (PMID 37185715, 2023). "In the cDNA microarray dataset analyzed with GEO2R, expression levels of ADAM32, ADAMTS6, and ADAM9 in HBL tumor tissues were 1.5-fold higher than in NCL." (PMID 36230656, 2022). "Upon pathologic activation, HSCs can promote tumor cell invasion by secreting MMPs to remodel existing ECM, producing additional collagen-rich ECM, and releasing ADAM9, which enhances tumor cell cleavage of surrounding laminin." (PMID 35954395, 2022). "In the U87‐ov‐USP39‐bearing tumor, the expression levels of USP39 and ADAM9 were upregulated but the expression levels of integrin β1 were downregulated compared with those in the U87‐ov‐Con‐bearing tumor." (PMID 33811456, 2022). "This novel style of biomimetic nanoparticles enabled miR-126-3p to effectively induce cancer cell apoptosis and inhibit tumor growth and metastasis by targeting ADAM9." (PMID 36171576, 2022). "ADAM9 is related to poor tumor grade and cell proliferation, migration, and invasion, possibly due to mediation of the interaction between cancer cells and fibroblasts." (PMID 35954348, 2022). "Forward ephrin-B signaling is a tumor suppressor pathway that prevents CRC progression, whereas ADAM9 is highly expressed in multiple types of solid tumors, and the expression levels often correlate with tumor progression." (PMID 35780836, 2022). "In vitro studies also confirmed that nanoparticles carrying miR-126-3p or ADAM9 knockdown inhibited tumor growth and metastasis by regulating cell proliferation, colony formation, migration, invasion, and EMT." (PMID 36171576, 2022).
tumor (continued). "In parallel, miRNA-dependent down-regulation of ADAM9, ADAM10 and ADAM17 was associated with reduced tumor progression, inhibition of cell proliferation and invasion and chemotherapy sensitization of HCC cells." (PMID 33805340, 2021). "Patients overexpressing ADAM metallopeptidase domain 9 (ADAM9) in the tumor tissues had significantly shorter survival compared to the ADAM9low group." (PMID 33648511, 2021). "Platelet integrin α6β1 directly interacted with tumor cell ADAM9, initiating platelet activation, granule secretion and mediating tumor cell dissemination." (PMID 34722319, 2021). "Increased expression of many Adamalysins including ADAM8, ADAM9, ADAM10, ADAM12 and ADAM17 was reported in HCC and associated with tumor progression." (PMID 33805340, 2021). "ADAM9 degrades several extracellular matrix (ECM) proteins indicating its pro-metastasis roles in tumour progression." (PMID 34187256, 2021). "Further studies on the molecular genetics of ADAM9, the tumor microenvironment, and cancer metabolism are required to understand the pro-tumoral effects of leukotriene D4." (PMID 32683508, 2021). "Taken together, these results reveal that nuclear ADAM9 functions as a transcriptional repressor by binding to promoters of genes involved in the negative regulation of angiogenesis, and thereby promotes tumor angiogenesis." (PMID 34671207, 2021). "As a membrane-anchored protein of the A-Disintegrin and Metalloproteinase (ADAM) protein family, the overexpression of ADAM9 in solid tumors has been correlated with aggressive tumor phenotypes and unfavorable clinical prognosis." (PMID 34646772, 2021). "Previous studies have demonstrated the relationship between ADAM9 expression and clinicopathological features, including disease prognosis, shortens overall survival, tumor grade, metastasis, and the development of resistance in various cancers, including HCC." (PMID 32683508, 2021). "One method to overcome this potential limitation would be to modify the ADAM9-MSNs with iRGD, a cyclic peptide involved in tumor targeting that has been shown to increase tumor invasion in PDAC." (PMID 34282781, 2021). "Six overexpressed and mutated tumor antigens associated with poor prognosis and infiltration of antigen presenting cells were identified in PAAD, including ADAM9, EFNB2, MET, TMOD3, TPX2, and WNT7A." (PMID 33648511, 2021). "ADAM9 over-expression has been suggested to be associated with HCC clinicopathological characteristics, and ADAM9 overexpression potentially results in tumor development, invasion, metastasis and poor prognosis." (PMID 34528498, 2021). "In ESCC, up-regulated DNA methyltransferase 1 contributes to tumor growth through ADAM9-mediated epidermal growth factor receptor (EGFR)-AKT signaling." (PMID 34671207, 2021). "Interaction of platelet-resident α6β1 with the disintegrin-cysteine-rich domain of tumor cell-derived ADAM9 also triggers platelet activation, α-granule release and P-selectin exposure, increasing tumor cell extravasation." (PMID 34322381, 2021). "Taken together, we reveal a novel role of ADAM9 as a stress-induced transcriptional regulator to undermine PAI-1 expression to promote tumor vascularization." (PMID 34671207, 2021). "ADAM9, a metalloprotease, is thought to promote tumor progression through enhancing metastasis and angiogenesis." (PMID 33664854, 2021). "ADAM9 is a metalloproteinase strongly expressed at the tumor-stroma border by both tumor and stromal cells." (PMID 32906814, 2020). "In mAIPC cell lines and an in vivo xenograft model, depletion of ADAM9 enhanced radiosensitivity and chemosensitivity of mAIPC cells, and suppressed tumor bone metastasis in vivo." (PMID 32719332, 2020). "In conclusions, our findings suggested the tumor-suppressive function of miR-1298 by targeting ADAM9 in BC, which suggested the potential of miR-1298 as a new regulator and therapeutic target for patients with BC." (PMID 33146718, 2020).
tumor (continued). "Taken together, the protein stability of ADAM9 is highly maintained by Naa10p to drive AIPC tumor outgrowth and metastasis." (PMID 33096780, 2020). "In a mouse model of PCa, ADAM9 was shown to play a critical role in tumor progression which was attributed to the ability of ADAM9 to cleave and release EGF and FGFR2 from cells." (PMID 32719332, 2020). "Since ADAM9 is widely expressed in the human body and regulates a variety of biological functions, ADAM9 also plays an important role in pathological diseases including degenerative, retinal, inflammatory and tumor biology." (PMID 33096780, 2020). "Restoration of MICA-NKG2D signaling by suppressing ADAM9 mRNA and its influence on the tumor microenvironment and its potential as a prognostic marker of human HCC patients should be investigated in future studies." (PMID 32245188, 2020). "A disintegrin and metalloproteinase 9 (ADAM9) is involved in tumor growth and invasion by liberating membrane-bound proteins by an enzymatic modification called “shedding”." (PMID 33176868, 2020). "The expression of OC in FFPE samples was examined by immunohistochemical methods, and the mRNA expression of ADAM9 in fresh tumor samples was examined by RT‐qPCR methods." (PMID 31793719, 2020). "We found the expression level of ADAM9 was markedly decreased in the OC tissue samples compared with the normal controls, and ROC analysis confirmed that ADAM9 can distinguish the OC tumor tissue from the adjacent non‐tumorous tissue." (PMID 31793719, 2020). "These evidences conclude the possibility of ADAM9 mediating chemoresistance in the advanced tumor stage." (PMID 33096780, 2020). "Four hundred and ninety-six of the analyzed proteins were similarly expressed in both genotypes, and only 53 proteins were altered at the tumor-stroma border of tumors from ADAM9−/− animals compared to WT controls." (PMID 32906814, 2020). "For example, the level of ADAM9 mRNA in tumors is related to the treatment response of the anti-tumor drug tamoxifen, and the high level of ADAM9 protein expression is an important indicator of poor prognosis." (PMID 32875951, 2020). "Recently, several studies reported that a number of micro (mi)RNAs can suppress tumor progression through destabilizing ADAM9 mRNA and attenuating translation." (PMID 32719332, 2020). "Overexpression of ADAM9 has been found in several cancer types and is correlated with tumor aggressiveness and poor prognosis." (PMID 33096780, 2020). "In recent years, the crucial roles of ADAM9 in tumor proliferation, angiogenesis, metastasis, and immune evasion have been broadly studied." (PMID 33096780, 2020). "Silencing Naa10p down-regulates the protein expression of ADAM9 to suppress tumor growth and metastasis in vitro and in vivo." (PMID 33096780, 2020). "ADAM9 was the most central gene in the green module, which can be induced under stress and further promote angiogenesis in tumours." (PMID 32091665, 2020). "We identified increased collagen type I as a result of ADAM9 deletion in the tumor microenvironment." (PMID 32906814, 2020). "Decorin levels were only modestly increased at the tumor-stroma border in ADAM9−/− mice, while reduced expression of collagen type XIV and fibronectin was detected." (PMID 32906814, 2020). "Silencing ADAM9 not only reduces the primary tumor size but also suppresses the metastasis rate to lung; in contrast, overexpressing ADAM9 accelerates primary tumor growth and promotes the metastasis to the lung." (PMID 33096780, 2020). "In this review, we show recent research data suggesting that changes in ADAM9 expression have been found in different tumor types." (PMID 32875951, 2020). "ADAM9 is not only reported to be up-regulated in tumor cells but also in the tumor microenvironment, which contains blood vessels, immune cells, and ECM." (PMID 33096780, 2020). "ADAM9 also contributes to disease progression by promoting tumor extravasation and migration ability." (PMID 33096780, 2020).
tumor (continued). "ERK signaling pathway can be activated by fisetin, which in turn down-regulates the expression levels of CTSS and ADAM9, thereby inhibiting cell proliferation, invasion and migration, and forming an anti-tumor metastasis effect." (PMID 32875951, 2020). "We observed ADAM9‐dependent shedding of HB‐EGF in both tumor cell lines as well as ADAM9‐dependent shedding of amphiregulin in MiaPaCa‐2 cells." (PMID 30556643, 2019). "We investigated the role of ADAM9 in tumor cell invasion using a basement membrane invasion colorimetric assay (CBA‐100‐C)." (PMID 30556643, 2019). "Multiple studies report the regulation of ADAM9 expression in tumors by supposedly tumor‐suppressive micro‐RNAs." (PMID 30556643, 2019). "This angiogenic role of ADAM9 is dependent on HB‐EGF shedding in tumor cells that signal in a paracrine manner (MEK/ERK signaling) to endothelial cells." (PMID 30556643, 2019). "The high prevalence of ADAM9 expression in patients with lymph node involvement and in patients with distant metastases showed that ADAM9 expression increased in aggressive tumours." (PMID 31030477, 2019). "To further investigate the ADAM9‐dependent difference in tumor volume, we resorted to a second tumor model." (PMID 30556643, 2019). "Positive ADAM9 immunostaining was also observed in tumours with a mean (SD) size of 40.13 (16.25) mm which indicates that the prevalence of ADAM9 expression is high in large (aggressive) tumours." (PMID 31030477, 2019). "The ADAM9 protein plays a role in basement membrane degradation and tumour metastasis in certain types of tumour." (PMID 31030477, 2019). "High ADAM9 expression in this patient cohort significantly correlated to advanced tumor grade (P = 0.027) and vascular invasion (P = 0.017)." (PMID 30556643, 2019). "In summary, our results characterize ADAM9 as an important regulator in PDAC tumor biology with a strong pro‐angiogenic impact." (PMID 30556643, 2019). "We aimed to characterize the role of ADAM9 in PDAC tumor biology using both in vitro and in vivo approaches." (PMID 30556643, 2019). "We report that ADAM9 is prominently expressed by PDAC tumor cells, and increased ADAM9 expression levels correlate with poor tumor grading (P = 0.027) and the presence of vasculature invasion (P = 0.017)." (PMID 30556643, 2019). "Tumors grown from PDAC cells with wild‐type ADAM9 levels (shControl) displayed a higher number of blood vessels (normalized per tumor area) than did tumors grown from shADAM9 PDAC cells." (PMID 30556643, 2019). "In the study, ADAM9 was highly expressed in high-grade tumours and in tumours with distant metastasis and lymph node involvement." (PMID 31030477, 2019). "The role of this integrin appears to be linked to its ability to directly interact with various types of tumor cells through the binding of ADAM-9." (PMID 28956830, 2017). "Although our results demonstrate ADAM9 proteins regulate VEGFA and ANGPT2 expression regardless protease activity, shedding function of ADAM9 is still important for pro-angiogenic factors generation to promote tumor growth." (PMID 29118335, 2017). "It has been previously reported that a secreted form of ADAM9 potently promotes cancer cell invasion by modulating tumor-stromal interactions." (PMID 27571068, 2016). "Human ADAM9 protein enhances adhesion and invasion of non-small lung tumors which mediates tumor metastasis." (PMID 27990250, 2015). "Previous studies have shown that ADAM9 affects tumor migration, invasion, and metastasis by modulating tumor cell adhesion." (PMID 26244545, 2015). "We also found that miR-126-3p overexpression downregulated ADAM9 protein expression in FTC-133-luc2 tumor xenografts that had been inoculated subcutaneously into the flanks of athymic nude mice and allowed to develop for 10 days." (PMID 26244545, 2015). "The background for the clinical significance of ADAM9 in tumor progression has been investigated by in vitro experiments." (PMID 25177692, 2014).
tumor (continued). "We also presented data indicating the feasibility of using in vivo lentivirus-delivered ADAM9 shRNA to reduce the tumor burden in animals." (PMID 23342005, 2013). "MiR-126&126* play their tumor suppression function through the direct inhibition of ADAM9 and MMP7, in turn impairing the activation of their common target heparin-binding EGF-like growth factor (HB-EGF)." (PMID 23437250, 2013). "Inhibition of ADAM17-mediated shedding reduces the growth of tumor xenografts in mice, and ADAM9 and -12 enhance tumour progression in transgenic mouse models of prostate and breast cancer." (PMID 21386996, 2011). "The additionally immunostained conventional tissue slides supported this estimation of a homogenous ADAM9 expression in tumour tissue." (PMID 18582378, 2008). "To confirm the validity of our study, we showed similar frequencies of loss of PTEN and SMAD4 expression in our PDAC samples, and higher levels of ADAM9 and βCAT in tumor compared with normal ducts as previously reported." (PMID 18254976, 2008). "For 30 additional cases, ADAM9 mRNA of microdissected tumour and normal tissue was analyzed via quantitative RT-PCR." (PMID 18582378, 2008). "Possible mediating effects on EGFR activity further support the notion of ADAM9 involvement in carcinogenesis and tumour progression." (PMID 18582378, 2008). "We found ADAM9 staining completely equal both tumour spots in 91.7% (98/107; in one case only one spot had sufficient tumour tissue), which we consider a high rate of concordance." (PMID 18582378, 2008). "This is not in line with our results from the separate mRNA-sample cohort, where only 10% of the normal tissue displayed higher ADAM9 expression than the tumour." (PMID 18582378, 2008). "The mean survival time of patients with PDAC without cytoplasmic ADAM9 expression was 30 months (±3; median 28±4), compared to 16 months (±2; median 11±1) for those whose tumours showed cytoplasmic ADAM9 expression (P<0.001)." (PMID 14997207, 2004). "Only cytoplasmic expression of ADAM9 and tumour grade were found to be independent prognostic factors for poor overall survival (cytoplasmic ADAM9: HR=2.85; 95% CI: 1.21–6.71, P<0.05; tumour grade: HR=4.81; 95% CI: 2.43–9.52; P<0.01)." (PMID 14997207, 2004). "The distribution pattern of ADAM9 in PDACs was related to the differentiation of the individual tumours." (PMID 14997207, 2004). "Thus, ADAM9 is upregulated in various tumour types, suggesting its significant potential as a therapeutic target." (PMID 40427200, 2025). "Notably, platelet glycoprotein VI (GPVI) interacts with tumor-derived galectin 3, integrin α6β1 binds to tumor ADAM9, CLEC-2 recognizes tumor podoplanin, and GPIIb/IIIa associates with tumor ανβ3 integrin." (PMID 40723273, 2025). "Inhibiting ADAM9 with a small-molecule inhibitor restricts disease progression in spontaneous models and, when combined with gemcitabine, induces significant regression of patient-derived tumours." (PMID 40427200, 2025). "Many tumor cell types exhibit overexpression of ADAM9, a transmembrane metalloproteinase." (PMID 39114075, 2024). "Additionally, in OSCC, an increased expression of DNA methyltransferase 1 plays a role in promoting tumor growth by influencing ADAM9-mediated activation of the epidermal growth factor receptor (EGFR)-AKT signaling pathway." (PMID 38673838, 2024). "Contrarily, tumor cell-derived ADAM9 confirmedly drives hMM progression, whilst stromal ADAM9 expression may have a protective function." (PMID 38891088, 2024). "Notably, when radiotherapy was combined with circ-ADAM9 inhibition, it exhibited significant inhibitory effects on tumor growth." (PMID 38317965, 2024). "Due to the function of ADAMs as a stress-triggered transcriptional repressor impacting plasminogen activator inhibitor-1 expression, ADAM9 might contribute to tumor vascularization." (PMID 38673838, 2024). "MiR-203 can be described as a tumor suppressor through downregulating ADAM9." (PMID 37185715, 2023).